CD4 (CD4 molecule)
Diseases named in the same sentence as CD4 in open-access papers (continued):
Sharing a sentence is not in itself a finding about the gene and the disease.
tuberculosis (continued). "HIV-tuberculosis co-infected and antiretroviral therapy-naïve adults with less than 250 CD4/mm3 were randomized to a nevirapine or efavirenz-based antiretroviral therapy initiated 4 to 6 weeks after starting tuberculosis treatment, and were then followed for 48 weeks." (PMID 24367678, 2013). "Previous reports have suggested a role for CD4+CD25+Treg cells in tuberculosis." (PMID 23826366, 2013). "Previous data indicated that measurement of CD4+ M. tuberculosis-specific TNF-α-only secreting cells might serve as an accurate biomarker of active tuberculosis." (PMID 23966657, 2013). "Interestingly, a low TH17 response in tuberculosis patients correlates with decreased IL-6 receptor expression on CD4+ T cells." (PMID 23350010, 2013). "There seem to be three primary effector functions for CD8+ T cells in tuberculosis as compared to CD4+ T cells; these include lysis of infected cells in the mucosal surfaces (e.g., macrophages and DCs), direct killing of the intracellular bacteria, and production of IFN-γ cytokines." (PMID 23213508, 2012). "In addition, a study on tuberculosis patients revealed higher numbers of such trifunctional CD4+ T cells in the patients compared to their exposed, but asymptomatic household contacts." (PMID 22412866, 2012). "There is evidence that CD4+ T cells may contribute both to the control of M. tuberculosis as well as of immunopathology, contributing to morbidity and mortality in tuberculosis disease." (PMID 23251798, 2012). "When the reason for testing was related to having risk factors for HIV in asymptomatic patients, like having sexually transmitted diseases or an HIV-positive partner, CD4 lymphocyte count at presentation was higher than patients with tuberculosis or HIV-related symptoms (P < 0.001)." (PMID 22611389, 2012). "Moreover, the incidence of active tuberculosis in HIV-infected individuals is inversely proportion to the number of CD4 T cells in peripheral blood." (PMID 22880090, 2012). "Effector CD4 T cells represent a key component of the host’s anti-tuberculosis immune defense." (PMID 22937086, 2012). "In individuals with latent Mycobacterium tuberculosis infection, CD4 depletion accelerates the progression from latent infection to active tuberculosis (TB), which, in turn, is believed to further fuel HIV replication rates due to elevated levels of pro-inflammatory cytokines." (PMID 22436147, 2012). "The essential role of IFN-γ is evident from the increased risk of tuberculosis in: (i) individuals with deficiency of IFN-γ and interleukin-12, which promotes Th1 cell differentiation; (ii) animal models depleted of CD4+ T-cell during the experimental infection; (iii) HIV-infected individuals." (PMID 23239994, 2012). "Extrapulmonary tuberculosis is more common in HIV-infected patients than in the general population regardless of the CD4 lymphocyte count and has been associated with high morbidity and mortality." (PMID 22966426, 2012). "Features such as multiple care sites (e.g. for HIV testing, CD4 count testing, and tuberculosis treatment), long wait times for appointments and receipt of test results, in addition to transportation barriers and medication costs are obstacles to effective linkage." (PMID 23176556, 2012). "Total, new and recurrent tuberculosis (TB) incidence rates by updated CD4 cell count strata." (PMID 22479548, 2012). "However, unlike Mycobacterium tuberculosis antigens which down-regulated IL-6R expression on CD4+ T cells from patients with tuberculosis, HBV antigen (HBcAg) up-regulated IL-6R expression on CD4+ T cells from patients with CHB." (PMID 21639870, 2011). "Observational prospective cohort data of patients on antiretroviral therapy (ART) are often used to estimate the relationship between time-varying CD4+ counts and incident clinical events such as tuberculosis (TB), death, opportunistic infections and malignancies." (PMID 22114687, 2011).
tuberculosis (continued). "A longitudinal study in Malawi has already indicated that lower CD4 cell counts were associated with higher incidences of pneumonia, sepsis, and tuberculosis but not of malaria(." (PMID 21235797, 2011). "Using the univariable analysis, the following factors were all associated with LEU: previous use of aminoglycosides, NSAID and acyclovir, current use of cotrimoxazole and HAART, high viral load, low Body Mass Index (BMI), low CD4 cell count, female gender and a previous history of tuberculosis." (PMID 21864389, 2011). "Noteworthy, patients with tuberculosis were enrolled for treatment at higher CD4 cell counts." (PMID 21504595, 2011). "In the 209 HIV-1 infected tuberculosis patients, 3 factors were significantly associated with clinical deterioration in univariate analysis: a lower CD4+ count, diagnosis of tuberculosis at the referral hospital, and antiretroviral treatment received during antituberculosis treatment." (PMID 20353569, 2010). "Extrapulmonary tuberculosis cases had lower median CD4+ lymphocytes at time of study than controls." (PMID 20196868, 2010). "Severe immunosuppression (CD4 cell count ≤ 50 cells/μL) at baseline (aHR 2.3; 95% CI 1.4 – 3.7) and active tuberculosis upon enrollment (aHR 1.8; 95% CI 1.0 – 3.6) were independent predictors of cohort losses to follow-up within the first 6 months after HAART initiation." (PMID 21532891, 2008). "Tuberculosis can occur at any stage of CD4+T cells depletion." (PMID 18826574, 2008). "An effective tuberculosis vaccine requires the development of memory CD4+ and CD8+ T cells." (PMID 18560543, 2008). "Two thirds (3/20 (65%) of the HIV tuberculosis patients had a CD4+T cells count of < 349 cells/mm3." (PMID 18826574, 2008). "More recently we have found that risk of mortality and risk of incident tuberculosis is strongly associated with the current CD4 cell count during ART rather than the baseline count (unpublished data)." (PMID 16551345, 2006). "It has been previously reported that peripheral blood mononuclear cells (PBMCs) from patients with active tuberculosis (TB) had significantly higher proportions of CD4+CD25high T cells and FoxP3 mRNA expression levels than cells from healthy controls." (PMID 40771802, 2025). "Increased expression of PD-1 in TB inhibits M. tuberculosis-specific CD4+ T cell function, macrophage phagocytosis, and intracellular killing contributing to TB reactivation." (PMID 40700327, 2025). "Among this, CD4+ T lymphocytes are key players in defending against tuberculosis (TB), mainly by producing interferon-gamma (IFN-γ), a cytokine critical for activating macrophages and controlling infection by MTBC." (PMID 40990013, 2025). "The data revealed that Mycobacterium tuberculosis-specific CD4 T-cell activation can distinguish active TB from latent TB with a sensitivity and specificity of 86%." (PMID 39471521, 2025). "Compared to patients with tuberculosis, those with proven PDH alone had a significantly higher proportion of severe immunosuppression, with 74% presenting CD4 + counts <50 cells/mm3 versus 48% in the TB alone group (p = 0.033)." (PMID 40961157, 2025). "This study, conducted in the Ashanti Region, employs a 5-state continuous-time Markov multistate model to analyze HIV progression based on CD4 cell counts, employing tuberculosis (TB) coinfection as a covariate." (PMID 40308565, 2025). "Type I signaling early during M. tuberculosis infection favors neutrophil swarming and limits CD4+ T cell–macrophage interactions in TB lesions, impeding TB disease control." (PMID 40986319, 2025). "The urine lipoarabinomannan tuberculosis LAM test was launched in 2015; the test is for active TB diagnosis in HIV‐infected persons with severe immunosuppression (CD4 < 200 cells/μL)." (PMID 40390769, 2025). "Suppression of type I IFN–dependent neutrophil responses facilitated CD4+ T cell accumulation within TB lesions, with type I IFN signaling impeding early M. tuberculosis control in both mouse strains." (PMID 40986319, 2025).
tuberculosis (continued). "Moreover, CD4+ T cell responses play a major role in anti-TB immunity, as depletion of these cells such as in the case of HIV infection, renders an individual more susceptible to tuberculosis." (PMID 40406522, 2025). "In immunocompromised individuals in low TB-endemic countries, the 2-year-risk for active tuberculosis was highest among PLHIV with detectable HIV-replication and low CD4-counts." (PMID 40823191, 2025). "Since CD4 T cells are key components of the immune response against M. tuberculosis, high CD4 cell counts can enhance responses to TB leading to more IDO activity." (PMID 38565993, 2024). "CD4+ T cells play a crucial role during primary M. tuberculosis infection, and TB vaccines increase CD4+ T cell responses." (PMID 38958367, 2024). "IFN-γ/IL-17 co-expressing CD4-Tcells are also considered important for protective immunity against tuberculosis with active TB patients having a significantly lower proportion of Th17 cells producing both IL-17 and IFN-γ than LTBI subjects." (PMID 39257584, 2024). "Improvement in the clinical course of DS tuberculosis due to the TB/FLU-06E immunotherapy was accompanied by enhanced activity of CD4+ and CD8+ Tem cells." (PMID 39065554, 2024). "In TB, CD4 and Th17 activity decreases as the disease progress, potentially due to adjustments in the local environment, where M. tuberculosis induces TGF-β production by the macrophages." (PMID 38165044, 2024). "The therapeutic effect of triple immunization with TB/FLU-06E in the DR tuberculosis model was accompanied by an increase in the counts of cytokine-producing CD4+ and CD8+ Tem cells predominately represented by IFN-γ-producing lymphocytes." (PMID 39065554, 2024). "The TB/FLU-06E immunotherapy impacts the persistence of TB antigens during tuberculosis infection triggering the dysfunction of CD4+ and CD8+ Tem cells." (PMID 39065554, 2024). "When CD4+ and γδ T cells from TB patients are cultured with M. tuberculosis, T cell apoptosis increases." (PMID 38004652, 2023). "The significantly decreased number of CD4+ T cells in patients with HIV makes them more susceptible to co-infections, including syphilis, tuberculosis (TB), and CMV." (PMID 38133300, 2023). "CD4+ T cells, which play a significant role in the development of anti-TB immunity, constitute a major immune cell population in M. tuberculosis-infected lungs." (PMID 36888692, 2023). "CXCL10 is upregulated in the human lung during active TB, recruiting CD4+ T cells to the lungs via CXCR3 during M. tuberculosis infection." (PMID 37896952, 2023). "However, when the body’s immune function is disordered, the surface molecules of Treg cells such as cytotoxic T lymphocyte-associated antigens will inhibit CD4+T and CD8+T cells activation, thus attenuated the macrophage clearance on MTB leading to the development of tuberculosis." (PMID 37103584, 2023). "Mycobacterium tuberculosis-specific IFNγ+CD4 T-cell responses in TB-IRIS patients are differentiated, highly activated, and potentially cytotoxic." (PMID 36726536, 2023). "Here, it is important to highlight the significant burden of tuberculosis in our setting, as PWH with TB tend to seek care later than expected, with low CD4 count, greatly contributing to early mortality." (PMID 35581552, 2022). "The risk of developing TB increases during HIV and M. tuberculosis co-infection suggesting that impairment of CD4 T cell-mediated immune responses reactivates the asymptomatic infection." (PMID 36064840, 2022). "This could be one of the causes of the high incidence of tuberculosis in nonresponders and the direct relationship with CD4+ T count, regardless of virological status." (PMID 35371095, 2022). "In bivariable logistic regression analysis, variables such as sex, CD4 count, ART adherence, IPT use, and BMI less than 18.5 kg/m2, believing that IPT use prevents TB, ever smoke, -ever drunk alcoholic beverages, and CPT were significantly associated with the outcome variable, Tuberculosis." (PMID 35931781, 2022).
tuberculosis (continued). "Low CD4 counts and short intervals between antituberculosis treatment and ART initiation are risk factors most consistently associated with TB-IRIS 14,48." (PMID 35175970, 2022). "T cells are crucial for the control of M. tuberculosis infection and CD4 T cells make an outsized contribution to immunity in the mouse TB model." (PMID 36409085, 2022). "CD27−CD38+IFN-γ+CD4+/CD4+ might be a potential biomarker for active tuberculosis diagnosis." (PMID 36457066, 2022). "One study in a mouse model of TB found that conventional T cell- (CD4 and CD8) produced GM-CSF was also protective and required for control of M. tuberculosis infection, though only when GM-CSF is not produced by other cell types." (PMID 35634283, 2022). "While research into how the immune system responds to HIV and Tuberculosis (TB) has historically focused on CD4+ and CD8+ T cells, unconventional T cells are emerging as interesting targets for immunologic studies." (PMID 34066765, 2021). "An increase in polyfunctional CD4+ T cells following BCG boosting with viral TB vaccines has been previously correlated with protection against M. tuberculosis with some, but not all, TB vaccines." (PMID 34793507, 2021). "We investigated the impact of active tuberculosis (TB), atopic status, and anti-TB treatment on the balance between Th1 and Th2 (type 2 CD4+ T helper) immunity." (PMID 34202662, 2021). "Fourth, this was a restricted patient population, purposefully selected for its high risk of TB-IRIS; only patients with a CD4 count ≤100 cells/μL and antituberculosis treatment for <30 days before starting ART were included in the trial." (PMID 33394813, 2021). "Further studies have shown that loss of B cells adversely affects development of Tuberculosis (TB)-specific CD4 memory precursor effector cells (MPECs) in TB vaccinated B cell deficient mice." (PMID 34177919, 2021). "In HIV- M tuberculosis co-infection, TB can occur at times when CD4+ T-cell numbers have reconstituted and viral replication is suppressed." (PMID 33995365, 2021). "As expected, a lack of virological suppression and low CD4+ cell count are associated with incident tuberculosis but, despite this, most tuberculosis episodes occurred among individuals who were virologically suppressed on cART and most after 12 months on cART." (PMID 32501837, 2020). "M. tuberculosis-mediated immunosuppression is a known phenomenon observed among TB patients resulting in low CD4 cell counts in both HIV-negative and HIV-positive patients." (PMID 32442166, 2020). "Incidence of tuberculosis among people with HIV has reduced with time; this is likely to be multifactorial, including association with overall reduction in tuberculosis incidence in the UK and with the higher CD4+ cell count at entry to the study and earlier start of cART." (PMID 32501837, 2020). "As T cell exhaustion has been shown to restrict the functionality of ESAT-6-specific CD4 T cells during M. tuberculosis infection, it is reasonable to think from a mechanistic standpoint that anti-exhaustion therapies will improve the immune response to tuberculosis." (PMID 32858811, 2020). "Being female, lower CD4 count, higher HIV viral loads, and coinfection with tuberculosis (TB) were strongly associated with moderate and severe anemia." (PMID 32258143, 2020). "HIV also specifically targets Mycobacterium tuberculosis (Mtb)-specific CD4 T-cells, resulting in impaired immune responses to TB in co-infected individuals." (PMID 32131556, 2020). "Most of the current tuberculosis (TB) subunit vaccines incorporate immunodominant antigens and at this point, it is poorly understood how the CD4 T cell subsets recognizing these antigens are affected during long-term infection." (PMID 33240275, 2020). "Recent data indicate that whole blood‐based assays to assess the phenotype of Mycobacterium tuberculosis (Mtb)‐specific CD4 T cells hold promise for this purpose and require further investigation in well‐characterised TB cohorts." (PMID 33005414, 2020).
tuberculosis (continued). "We investigated the levels and ratios of eicosanoid mediators and their cellular sources, monocyte subsets and CD4 T cells in Tuberculosis (TB) patients with various clinical states of Mtb infection." (PMID 33304347, 2020). "Tuberculosis: Decisions regarding the timing of ART in patients with TB should generally be based on the CD4+ count." (PMID 33101723, 2020). "The WHO-endorsed immunodiagnostic Alere Determine Lipoarabinomannan Ag-test (LAM-test) detects Mycobacterium tuberculosis complex LAM in urine, and its use is recommended for TB diagnosis among HIV co-infected individuals with low CD4 T-cell counts." (PMID 31784649, 2019). "CD4+ T cells are important components of TB granuloma and play a central role in restricting M. tuberculosis infection." (PMID 31849981, 2019). "Studies in TB-HIV co-infected adults to characterize functional defects in CD4+ T-cells has increased our understanding of the role of these cells in the immune response to M. tuberculosis." (PMID 31294001, 2019). "Therefore, LAM testing may miss some patients with tuberculosis, particularly those with CD4 cell counts >100/μL." (PMID 31024977, 2019). "The central dogma suggests that within TB lesions, infected macrophages are activated by antigen-specific CD4+ T cells that secrete interferon-gamma (IFN-γ), restricting the growth and dissemination of Mycobacterium tuberculosis (Mtb)." (PMID 31825836, 2019). "The results we obtained on M. tuberculosis T-cells functional profile were also in agreement with those obtained in previous studies, as we found that CD4+ T-cell only producing TNF-α in response to PPD were increased in active TB patients." (PMID 30687314, 2018). "Inclusion criteria included CD4 count less than 100 cells/μl, microbiologically confirmed TB or clinical diagnosis with symptomatic response to antituberculosis treatment, and starting ART within 30 days after starting antituberculosis treatment [12▪▪]." (PMID 30124473, 2018). "The most common pulmonary condition was tuberculosis seen in 53 (57.6%) of the participants and it was more prevalent for CD4 cell count between 100 and 199 cells/mm3, followed by bacterial pneumonia in 25 (27.2%) participants, it was most prevalent for CD4 count between 300 and 399 cells/mm3." (PMID 29941015, 2018). "In summary, our findings on surface homing markers such as CD27 and CCR4 on M. tuberculosis specific CD4+ T-cells gather the required features for using them as potential TB biomarkers." (PMID 30687314, 2018). "Moreover, this study provides further evidence that good long term immunological and virological outcomes in low resources settings are possible, even for patients starting ART with low CD4 values and with a high proportion of patients with current or previous co-infections like tuberculosis." (PMID 29420652, 2018). "In the present study, of the total TB cases, 42.9% of tuberculosis infection occurred in low CD4 level (<200/μl)." (PMID 29997701, 2018). "The a priori goal of this secondary objective of A5221 was to determine if baseline measures of 1) nutrition or 2) inflammation and immune activation could be related to death in the participants initiating therapy for HIV and tuberculosis who had low CD4 counts (< 50 cells/mm3)." (PMID 29770360, 2018). "Such rapid detection makes it possible to identify differences between active tuberculosis and latent infection: more CD4+ T cells produced IFNG or TNFA mRNA as early as 2 h post-stimulation in active TB." (PMID 30283456, 2018). "Several studies in experimental mouse models and in HIV-infected patients have underscored the essential role of CD4+ T-cells and Th1 immunity in protection against tuberculosis (TB)." (PMID 29875774, 2018). "A continuous depletion of CD4 cells results in opportunistic infections, for example tuberculosis (TB)." (PMID 29343268, 2018).